C3 (complement C3)
Diseases named in the same sentence as C3 in open-access papers (continued):
Sharing a sentence is not in itself a finding about the gene and the disease.
metabolic syndrome (continued). "Studies have shown that serum complement C3 is an early marker of metabolic syndrome in obese people." (PMID 29299442, 2017). "This study sought to evaluate the serum C3 concentration in women with normal weight obese (NWO) syndrome compared to controls as well as the relationship between complement C3 and body fat mass and the components of metabolic syndrome." (PMID 29299442, 2017). "Plasma concentrations of C3, C4, and the C4/C3 ratio have been linked to classic CVD risk factors, low-grade inflammation, and the metabolic syndrome." (PMID 28567671, 2017). "Blood samples were then collected and analyzed for fasting serum concentration of lipid components of metabolic syndrome, insulin, serum complement C3 and High sensitivity C reactive protein (hsCRP)." (PMID 29299442, 2017). "In another study, complement C3 was strongly associated with IR, independent of the other components of metabolic syndrome." (PMID 36155123, 2023). "Moreover, in platelet-rich rat plasma, C3 reduced platelet aggregation, and in a hamster model of chronic dyslipidemia, the C3 administration reduced whole-blood aggregation." (PMID 35990779, 2022). "So taken together, in our prospective cohort, systemic concentration of the major complement components C3 and C4, but not their activators or activated products, were associated with incident metabolic syndrome." (PMID 30132263, 2018). "This is for instance illustrated by the observation that the association of complement C3, but not of C4, with incident metabolic syndrome was partly explained by liver function." (PMID 30132263, 2018). "In addition, the plasma concentrations of several complement factors (i.e., C3, C3a, FD, FH, properdin, C4) were higher in participants with the metabolic syndrome." (PMID 30132263, 2018). "High levels of the complement component C3, point of convergence of the three complement activation pathways, may also be related to the hyperinflammatory state, as described in acute infections and metabolic syndrome." (PMID 35425776, 2022). "However, given the effects of intracellular complement activation on TH1 metabolism, intracellular C3 activation will likely affect metabolism in many cell types and, as such, potentially affect the metabolic dysregulation that characterizes the metabolic syndrome." (PMID 30132263, 2018). "A positive correlation between serum complement C3 levels and prevalence of NAFLD was also observed among lean and metabolic syndrome-free participants." (PMID 27029598, 2016). "In this study, we provided evidences for the first time that serum complement C3 level is independently associated with NAFLD in non-obese and metabolic syndrome free population, and the C3 levels are positively associated with severity of NAFLD." (PMID 27029598, 2016).
vasculitis (36 papers, 2010 to 2026). "Collectively, C3 activation and deposition constitute not only a hallmark pathological feature of vasculitis but also a determinant of disease activity, tissue injury, and clinical outcome." (PMID 41187099, 2025). "Clinical studies have demonstrated that the level of complement C3 activation is closely linked to disease activity and organ injury in vasculitis." (PMID 41187099, 2025). "In this regard, low levels of C3 are associated with a more aggressive histological presentation of vasculitis and a worse renal prognosis in several models." (PMID 39597819, 2024). "CFI deficiency is thus now added to the growing list of monogenic causes of vasculitis and should always be considered in vasculitis patients found to have persistently low levels of C3 with normal C4." (PMID 29696024, 2018). "Heterozygous GOF mutations in C3 are now added to the list of genetic complement deficiencies causing vasculitis such as C1q, C1r, and C1s deficiency, complement factor I deficiency and complement C2 and C4 deficiency." (PMID 30443255, 2018). "In summary, we expand the spectrum of monogenic complement deficiencies that cause vasculitis by describing a family with monoallelic p.R1042G mutation in C3 causing cutaneous vasculitis and digital ischaemia." (PMID 30443255, 2018). "C3 deficiency due GOF C3 mutations is thus now added to the growing list of monogenic causes of vasculitis and should always be considered in vasculitis patients found to have persistently low levels of C3 with normal C4." (PMID 30443255, 2018). "We induced anti‐myeloperoxidase vasculitis in mice and confirmed a role for complement activation by demonstrating protection in C3‐deficient mice." (PMID 27235854, 2016). "The association with hypocomplementemia (low C3/C4) reflects complement consumption and signals heightened systemic activity; clinically, it may herald vasculitis and adverse outcomes." (PMID 41458824, 2025). "Glomerular deposition of C3 in MPO-ANCA-vasculitis has been associated with worse renal outcomes." (PMID 40430184, 2025). "Thus the spectrum of monogenic vasculitis continues to expand, and mono-allelic C3 GOF mutations should now be considered in patients with ANCA negative vasculitis, particularly when associated with low serum C3, but normal C4 levels." (PMID 30443255, 2018). "In addition, glomerular deposition of C3 in MASP‐2‐deficient mice with anti‐MPO vasculitis was similar to that in wild‐type mice." (PMID 27235854, 2016). "Importantly, a C3 inhibitor aimed at sites of complement activation is presently undergoing phase 2 clinical trials for anti-neutrophil cytoplasmic autoantibody (ANCA)-associated vasculitis and renal disease." (PMID 39682736, 2024). "Ifng then enhances C3 and C4 (and possibly Cfb, Cfh, and Fcna) expression, which leads to neutrophil activation and causes a cytokine/chemokine storm, inducing damage and necrosis of vascular endothelial cells, severe inflammation and finally, a lethal vasculitis." (PMID 24063402, 2013). "Several studies have shown that deposition of certain complement elements (C3, C4, C1q, factor B, properdin, and CAM) in renal biopsies from patients with vasculitis is associated with increased proteinuria and worse renal function." (PMID 39597819, 2024). "In summary, the present study together with the previous one suggests that mast cells are a marked source for C3 and C3b that is further cleaved by accumulating CFI+ cells to iC3b in the early vasculitis lesion." (PMID 35747245, 2022). "Because the number of C3c+ mast cells correlated to the score of iC3b in the nonlesional skin, these cells can be assumed to be one marked source for C3, C3b, and iC3b in the very early events of vasculitis." (PMID 35747245, 2022). "It has also been demonstrated that plasma from Vasculitis patients has significantly more C3- and C9-positive endothelial MVs than controls." (PMID 39086962, 2022).
vasculitis (continued). "These events can be seen in direct immunofluorescence (IF) staining of an early vasculitis lesion as positive vessel wall staining of immunoglobulins; complement products, including C1q and C3; and fibrin." (PMID 35747245, 2022). "Low levels of complements C3 and C4 protein concentrations detected in SLE patients are also highly associated with LN and vasculitis in SLE patients." (PMID 33644084, 2020). "A diagnosis of vasculitis was suspected on the basis of the clinical and biological course (skin lesions, arthralgias, proteinuria, low complement C3 and C4 fractions, etc.)and pulse steroid therapy was prescribed." (PMID 20706684, 2010). "Therefore, mast cells have most of the machinery to initiate and perpetuate the C3-mediated reaction in vasculitis once activated." (PMID 35747245, 2022). "C3 and C4 are also known to be deposited in late vasculitis lesions." (PMID 29236760, 2017). "Furthermore, the H4-lpr mice displayed vasculitis with perivascular cell infiltration, glomerular deposition of IgG and complement C3, by contrast, B6-lpr mice had minor kidney lesion pathology." (PMID 29321778, 2017). "Taken together, our results suggest that CAWS administration induces Dectin-2 mediated CAWS-vasculitis in both B6 and DBA/2 mice and the expression of Ifng, but only in DBA/2 mice, which led to increased expression of C3, C4, Cfb, Cfh, and Fcna and an associated increase in lethality in these mice." (PMID 24063402, 2013). "Furthermore, the partial inactivation of chymase in vasculitis allows survival of C3." (PMID 35747245, 2022). "Based on our findings that complement components C3 and C4 indicate vasculitis manifestations to distinct renal compartments in ANCA GN, it is attractive to speculated that innate immunity facilitates kidney injury by pathomechanisms attributed to specific complement system components." (PMID 34205415, 2021). "A total of 215 skin biopsies from patients with suspected immune-mediated vesiculobullous diseases, vasculitis, or dermatoses were examined using HP and DIF for the presence of IgG, IgA, IgM, and complement component C3 deposits." (PMID 40546482, 2025). "In the case of C3 fragments after adjustment for proteinuria, highest excretion was seen in MCD, C3G, DKD, FSGS, MGN, LN and vasculitis." (PMID 34941814, 2021). "In accordance with our previous results, complement C3 deposits and NETosis markers were significantly elevated in TSP-1-KO mice, further supporting the role of TSP-1 in complement regulation and subsequent NETosis in vasculitis." (PMID 40338657, 2025). "Neither complement levels (C3, C4), serum vasculitis markers (von Willebrand factor and D-dimer), nor autoantibodies differed significantly between males and females." (PMID 35998241, 2022). "Histological analysis revealed that pristane treatment induced vasculitis in Tank−/− mice, but not in WT, as evidenced by the fragmentation of leukocytes and IgM and complement C3 deposition in perivascular lesion." (PMID 34819357, 2022). "Initial vasculitis workup was negative for antinuclear antibody (ANA), complement component 3 (C3), and antineutrophil cytoplasmic antibodies: P-ANCA, C-ANCA." (PMID 33854857, 2021). "In addition, the similar kidney outcome irrespective of C3 deposition, as it is suggested in some studies, does not justify the use of complement fractions as specific biomarkers of ANCA-vasculitis outcomes, at least at present." (PMID 40430184, 2025). "Patients in the ESRD group also had a higher serum creatinine level, 24-h protein excretion, Pediatric Vasculitis Activity Score (PVAS), and a lower level of estimated glomerular filtration rate (eGFR), hemoglobin, and complement C3 than had those in the non-ESRD group (P < 0.05)." (PMID 33981654, 2021).
chronic kidney disease (35 papers, 2013 to 2026). Impairment of the renal function secondary to chronic kidney damage persisting for three or more months. "We also investigated the association of C3 and C1q deposits in kidney tissues with a composite outcome of end-stage renal disease or a 50% reduction in the estimated glomerular filtration rate (eGFR) in DN patients." (PMID 35479942, 2022). "For example, long-term METH use causes chronic kidney disease due to the deposition of IgM and C3 complement." (PMID 34109323, 2021). "An association was demonstrated between mesangial C3 deposition, decreased serum C3 levels, and doubling of serum creatinine or reaching end-stage renal disease in a cohort of 343 IgAN patients." (PMID 28673452, 2017). "Of the 221 patients with a mean follow-up of 53.3 months, the risk of reaching end-stage renal disease (ESRD) was significantly higher in patients with low serum C3 level (p < 0.001)." (PMID 28642464, 2017). "We observed that low serum C3 level at diagnosis was strongly linked to patient mortality and the risk of end-stage renal disease." (PMID 27391243, 2016). "Furthermore, the ratio of plasma galactose-deficient IgA1 and C3 was independently associated with progression to chronic kidney disease or kidney failure in a large cohort of IgAN patients from China." (PMID 34379175, 2021). "We evaluated whether isolated C3 hypocomplementemia (i-LowC3), defined as serum low C3 (≤80 mg/dL) and normal C4 (>10 mg/dL) six months after kidney biopsy is associated with subsequent risk of chronic kidney disease (CKD), End Stage Kidney Disease (ESKD) or death." (PMID 41019087, 2025). "In fact, C3G is a rare chronic kidney disease mediated by a dysregulation of the AP, which is due to uncontrolled C3 and/or C5 convertase activation, leading to C3 deposits and intra-glomerular inflammation." (PMID 40895567, 2025). "This tubular C3 overproduction can, through local pro-fibrotic effects, influence the progression of chronic kidney disease." (PMID 39684261, 2024). "It seemed that belonging to the cluster consisting of patients with normal levels of blood C3, sC5b-9, and intensive renal biopsy C3 staining was an independent determinant of end-stage renal disease." (PMID 36899849, 2023). "Clinically, MCP mutations rarely progress to end-stage renal disease (ESRD); this is in contrast to the poor renal prognosis associated with FH and C3 mutations." (PMID 30714990, 2019). "The present study highlights an association between serum complement C3 level measured at AAV diagnosis and the risk of end-stage renal disease and mortality." (PMID 27391243, 2016). "Other studies disclosed that high circulating levels of C3 and C3a are associated with an increased cIMT, peripheral artery disease, renal arteriolosclerosis in non-diabetic chronic kidney disease, and increased risk of myocardial infarction." (PMID 38978073, 2024). "If complement inhibition is not applied within 4–5 relapses after MCPggaac haplotype onset, with/without adjacent mutations (CHF, CD46, C3), proteinuria, renal damage, and eventually chronic renal failure will occur." (PMID 37685848, 2023). "High C1q, C3, and C5b-9 expression in glomeruli was also related to the progression of chronic kidney disease to kidney failure, although glomerular MBL expression was low irrespective of whether the patient had the composite outcome." (PMID 35479942, 2022). "This patient progressed to end-stage renal disease, requiring renal dialysis; and diffuse proliferative GN with endocapillary proliferation without crescents or necrosis (N = 2), immunofluorescence studies being positive for C3 and IgG (N = 1) and IgM (N = 1)." (PMID 26817911, 2016). "We identified the hub genes of CKD (Fn, Timp1, C3, Apoe, Trf, Fbn1, FGG, Penk, Ckap4, and Gpc3) through multiple bioinformatics analyses and successfully verified their expression in a mouse chronic kidney disease model." (PMID 40564035, 2025).
chronic kidney disease (continued). "The effect of CFHR3 gene mutation on renal interstitial compartment presenting as chronic interstitial compartment should be considered in cases of young-onset chronic kidney disease with a strong family history of ESRD and low C3 levels." (PMID 39184759, 2024).
lung carcinoma (35 papers, 2011 to 2025). "In this study we discovered that a high level of serum C3 was statistically and independently associated with lung cancer in CPFE patients." (PMID 36769748, 2023). "First, pack-years, family history of cancer, fibrinogen and serum C3 were independently associated with the prevalence of lung cancer in patients with CPFE." (PMID 36769748, 2023). "Pack-years, family history of cancer, and levels of fibrinogen and serum C3 were independently associated with lung cancer in patients with CPFE." (PMID 36769748, 2023). "Binary logistic regression analysis showed that complement C3 was independently associated with the presence of lung cancer in CPFE patients." (PMID 36769748, 2023). "Though C3 was reported to associated with CD4+ and CD8+ T lymphocytes in lung cancer, however, a majority of studies suggested that C3 play an oncogenic role in multiple cancers." (PMID 33732636, 2020). "The elevated plasma levels of C3, C9 and C4d complement proteins were associated with shorter survival of patients with lung cancer." (PMID 30841875, 2019). "Furthermore, in ovarian and lung cancer higher tumoral C3 and/or C5aR mRNA expression were associated with decreased overall survival." (PMID 29423024, 2018). "The present study also indicated that the relative mechanisms of SLC34A2 in A549 lung cancer may be associated with the activation of the complement alternative pathway (C3 and C4b) and upregulation of the expression of SELENBP1, TXNIP, PDZK1IP1 and DUSP6." (PMID 25017204, 2014). "Therefore, the apparent difference in complement C3 abundance observed in the screening was reflecting the degree of proteolytic degradation associated with lung cancer." (PMID 21473792, 2011). "Interestingly, FH autoantibodies found in patients with non-small cell lung cancer recognize the peptide PIDNGDIT in FH SCR19, inhibit FH binding to lung carcinoma cells and cause increased C3-deposition when binding to FH that is already bound to the cancer cell surface." (PMID 33986750, 2021). "To identify the biological role of C3 in lung cancer resistance to PTX, we knocked down C3 expression in A549-PTX cells and found that the viability and colony formation capability of the C3-insufficient cells were dramatically decreased after PTX treatment." (PMID 37291119, 2023). "The presence of lung cancer in patients with high complement C3 was significantly higher than that in patients with low C3." (PMID 36769748, 2023). "In the context of leptomeningeal metastasis, the upregulation of complement component 3 (C3) has been attributed to the infiltration and survival of breast and lung cancer cells in the CSF microenvironment." (PMID 36980770, 2023). "The overexpressed C3 in blood and downregulated C3 in tumor tissues were observed in lung cancer patients, and related to poorer prognosis." (PMID 31333911, 2019). "A proposed five-gene diagnostic signature, including KRT5, MUC1, TREM1, C3, and TMPRSS2, as well as an eight-gene classifier for lung cancer subtypes, exhibited a high predictive accuracy of 0.936 during testing on 2556 adenocarcinoma samples and 1630 squamous cell carcinoma samples." (PMID 38612418, 2024). "Another study revealed that Th2 cells stimulate lung cancer metastasis by activating neutrophils through complement C3, and our findings also identified that BHLHE40 significantly correlated with Th1 and Th2 cell differentiation, Th17 cell differentiation and PD-1 checkpoint in GO and KEGG analyses." (PMID 37773521, 2023). "Comparing the high C3 group to the low C3 group in lung cancer patients, we found that the levels of serum CRP (82.37 (61.89, 90.91) vs. 51.90 (43.19, 60.21), p < 0.05) and IL-6 (89.80 (66.57, 127.13) vs. 53.69 (31.61, 57.68), p < 0.05) were significantly higher in the high C3 patients." (PMID 36769748, 2023). "Taken as a whole, these imply that the C3 protein may contribute to the development and progression of lung cancer." (PMID 25686824, 2015).